MDM2 (MDM2 proto-oncogene)
Diseases named in the same sentence as MDM2 in open-access papers (continued):
Sharing a sentence is not in itself a finding about the gene and the disease.
cancer (continued). "The rate of both genes MTHFR C/T (χ2 = 2.4, df = 1, P = .12) and MDM2 T/T (χ2 = 2.6, df = 1, P = .11) had a tendency to decrease in samples of patients diagnosed with stage III-IV cancer." (PMID 29423041, 2018). "Among diverse cancers (N = 102,878), high TMB status was significantly less frequent in patients with MDM2 amplification than in the MDM2 wild-type population (2.9% [105 of 3,650] v 6.5% [6,492 of 99,228], respectively; P < .001)." (PMID 30148248, 2018). "A recent report claimed that the combined blockage of Akt/mTOR and MDM2 augments cell apoptosis and differentiation in GBM cancer stem cells." (PMID 29769662, 2018). "A mixture of siRNA(s) targeting MDM-2 gene along with other oncogenes, c-myc and VEGF that initiate and flourish the metastatic behavior of a cancer, were encapsulated with nanoparticles formulated by protamine, cationic lipid and PEG." (PMID 29861465, 2018). "The top three non-cancer disease genes regulated by the co-functional module and mapped to the pathways are MMP2, VEGFA and CASP8, while for the cancers are BCL2, MDM2 and VEGFA." (PMID 28340554, 2017). "By carrying the three SiRNA strands (AKT, MDM2 and Survivin) into triple negative breast MDA-MB-231 cancer cells, cell number had reduced by up to ~82% within 24 hours solely from one single administration of 32 picomoles." (PMID 28400564, 2017). "We believe development of these MDM2-VEGF inhibitors as potential anticancer drugs for clinical use is worthwhile and represents a novel strategy for improving cancer outcome." (PMID 28274247, 2017).
cancer (continued). "Our findings that the N- and C-termini of RPL22/eL22 play distinct roles in MDM2 inhibition may also explain why most of the RPL22/eL22 mutations are deletion mutations, as otherwise the inhibitory effect on MDM2 by different domains of RPL22/eL22 may not be eliminated completely in cancer cells." (PMID 29207594, 2017). "During the carcinogenesis of 26 kinds of cancers, averagely more than 70% of those cancers relate to the dysfunction of the three genes (BCL2, MDM2 and VEGFA)." (PMID 28340554, 2017). "The two murine double minute (MDM) family members MDM2 and MDMX are at the center of an intense clinical assessment as molecular target for the management of cancer." (PMID 28673313, 2017). "Many other cancer-related genes show distinct alternative splicing profiles in cancers, including BRCA1, BRCA2, MDM2, KLK3 (also named prostate-specific antigen, PSA), and fibroblast growth factor receptors (FGFRs)." (PMID 28257090, 2017). "The results presented here support the idea that targeting the MDM2 pathway by fulvestrant treatment of estrogen-receptor positive breast cancers that are not resistant to fulvestrant may be an excellent mechanism to target the cancer at multiple estrogenic hubs." (PMID 28615518, 2017). "In combination with DNA damage-inducing chemotherapy or with MDM2 antagonists (such as nutlin-3), WIP1 inhibition promotes cancer cell death or senescence, while it has little effect on viability of healthy cells." (PMID 28439615, 2017). "In contrast to findings of other blood-based studies, we found at least four NSCLC-associated markers that were involved in Ras/MAP kinase and cell growth control pathways highly relevant to cancer: DUSP6, GRB2, MDM2, and NF1." (PMID 27418131, 2016). "To further validate the disruption of microRNA-mediated repression by RNA editing, we selected one cancer cell line with high RNA editing level (BT474) and one cell line (MDA-MB-231) with low RNA editing level at the 3′ UTR region of MDM2." (PMID 26980570, 2016).
cancer (continued). "Overexpression of MDM4 has also been reported in various cancers, and MDM4 inhibitors were recently developed along with dual inhibitors against MDM2 and MDM4." (PMID 27659536, 2016). "Recently, the relative expression of MDM2, MDM2-B, MDMX (MDM4), and MDMX-S has been found to predict heterogeneous responses of Nutlin-3 in cancer cells." (PMID 27129163, 2016). "In the present study, we successfully genotyped the MDM2 SNP55C>T (rs2870820) in a total of 10,751 Caucasian (Norwegian) individuals (3,725 healthy controls and 7,026 cancer cases) as well as 299 healthy African-Americans (for ethnic comparison)." (PMID 27624283, 2016). "Currently, the search for specific E3 inhibitors (e.g., MDM2, IAP, and SKP2) is a promising strategy for chemotherapy or the prevention of cancer." (PMID 27791197, 2016). "Recently, we identified new reversible compounds dual-targeting MDM2 and TSPO, two proteins that are both up-regulated in GBM so contributing to cancer cell resistance to physiological apoptosis." (PMID 26761214, 2016). "Our studies demonstrated a mutual regulation of MDM2 protein and XIAP mRNA in cancer cell growth and disease progression." (PMID 25888903, 2015). "MDM2 is a suitable target TAA, as it is involved in oncogenesis and is overexpressed in a high proportion of cancers." (PMID 25539815, 2015). "In fact, blocking or disrupting the interaction between the MDM2 RING protein and XIAP IRES RNA by a specific antisense leads to inhibition of cancer cell growth and increased apoptosis." (PMID 25888903, 2015). "Enforced overexpression of the XIAP IRES RNA in cancer cells increased the expression of both MDM2 and XIAP, which led to cancer cell survival and resistance to apoptosis." (PMID 25888903, 2015).
cancer (continued). "For example, genes with Motif 1 in Molecular Mechanisms of Cancer pathway include MAPK1, BRAF, SMAD2, FZD5, FZD8, NOTCH1 and LRP1, whereas genes with Motif 2 and/or Motif3 in the same pathway include LRP5, LRP6, MDM2, CTNND1, SMAD3, SMAD4 and SMAD7." (PMID 26040697, 2015). "The XIAP mRNA and protein reciprocally regulate MDM2 protein stability through different mechanism, which is likely a homeostasis for MDM2 expression, suggesting that the interaction of the two factors and their deregulation may play a critical role in cancer pathogenesis." (PMID 25888903, 2015). "ASF1A accumulated in cancer cell lines with downregulated RAD6 levels, although the MDM2 levels were upregulated." (PMID 26336826, 2015). "Both MDM2 and MDM4 function as oncogenes and their deregulated expression has been reported in various types of human cancers, including soft tissue sarcoma, breast cancer, retinoblastoma, and melanoma." (PMID 25621298, 2014). "For example, MDM2 and IAP are highly expressed in several human cancers and inhibitors for these enzymes are being evaluated in clinical trials." (PMID 24870930, 2014). "Including transcripts from MAT2A and MDM2, 27.8% of significant DE transcripts in PBAFB were annotated to genes with known roles in cancer or apoptosis." (PMID 24979717, 2014). "For example, MDM2 is a positive regulator of the anti-apoptotic factor XIAP, binding the XIAP IRES to induce XIAP mRNA translation, which results in resistance of cancer cells to radio-chemotherapy." (PMID 24968304, 2014). "Recently, small molecular inhibitors of MDM2 and MDM4 have been developed and are currently being evaluated in clinical trials for several cancer types." (PMID 24874471, 2014). "The expression of MCSF in U87MG cells leading to cancer stem cell population further aggravated the resistive phenotype through an elevated increase in the expression of ABCB1 and mdm2 as compared to the treated U87MG cells." (PMID 24391839, 2013).
cancer (continued). "The MDM2-mediated IGF-1R ubiquitination activates the ERK pathway and leads to the cancer resistance to PPP." (PMID 24182354, 2013). "In the spleen, 8/84 cancer-related genes were affected in FLT mice compared to AEM controls (P<0.05; up: Cdkn2a; down: Birc5, Casp8, Ctnnb1, Map2k1, Mdm2, NFkB1, Pdgfa)." (PMID 24069384, 2013). "There have been development of inhibitors to some of the key intracellular molecules, kinases, e.g., MDM2 (murine double minute 2), ALK (anaplastic lymphoma kinase) and PARP (poly [ADP-ribose] polymerase) as anti-cancer therapeutics." (PMID 22475564, 2012). "MDM2 amplification is a key feature of WD/DDLPS and is amplified and overexpressed in a number of other cancers, highlighting its importance in tumorigenesis (as reviewed)." (PMID 21253554, 2011). "Overexpression of ubiquitin ligases including MDM2, COP1 and ARF-BP1 has been observed in human cancer, while downregulation of others such as FBW7 or Rnf8 promotes tumorigenesis." (PMID 22125490, 2011). "For MDM2 SNP309, a significant difference of 9.0 years in the average age of cancer diagnosis was observed between GG/GT and TT carriers (18.6 versus 27.6 years, P = 0.0087)." (PMID 20520810, 2010). "p73 activity can also be regulated by interaction with several cellular partners such as Mdm-2, Yap, ASPP family proteins and these are often altered in cancer cells." (PMID 19293798, 2009). "“Transcriptional misregulation dysregulation in cancer” shows genes such as NCOR1 and MDM2." (PMID 40621499, 2025).